MIR548AY (microRNA 548ay)
Synonyms: hsa-mir-548ay
Gene: MicroRNA gene on chromosome 3 (32,506,283 to 32,506,389, reverse strand). Ensembl gene ENSG00000276147.
Homologues: Paralogues in human: MIR548AZ (68% identical), MIR548Z (68% identical), MIR548AN (66% identical), MIR548H3 (66% identical), MIR548X2 (64% identical), MIR548AA1 (64% identical), MIR548K (62% identical), MIR548F3 (59% identical), MIR548N (59% identical), MIR548F1 (56% identical), MIR548AH (55% identical), MIR548AX (55% identical), and 13 more.